INS (insulin)
Diseases named in the same sentence as INS in open-access papers (continued):
Sharing a sentence is not in itself a finding about the gene and the disease.
Obesity (continued). "The establishment of the early hyperinsulinemic condition, found in the PND15 of MSG-obese animals, may indicate the anticipation of the dynamic phase of obesity, where the induction of increased glucose uptake by insulin-responsive tissues seems to occur." (PMID 36902158, 2023). "Based on the results of the in vitro experiments and our earlier data on the pharmacodynamics of compound PI4, we studied the anorexigenic effect of compounds 1–4 and their influence on glucose homeostasis, as well as insulin and leptin resistance, in rats with diet-induced obesity." (PMID 36901928, 2023). "In patients with OSA, alterations in FFA metabolism may be potentiated by exposure to intermittent hypoxia and further compounded by the presence of obesity to have a profound effect on adipose tissue and whole-body insulin sensitivity." (PMID 39434962, 2023). "Though obesity-induced increases in myocardial lysine acetylation are positively correlated with increases in fatty acid oxidation and reductions in insulin sensitivity in HFD-fed mice, changes in protein acetylation do not always track with increases in fatty acid oxidation." (PMID 36978133, 2023). "Interestingly, heterozygous Pik3r1+/− mice are also protected from obesity; however, in contrast to Pik3r1+/R649W mice, they remain insulin sensitive." (PMID 37628845, 2023). "Recent research suggests that obesity is not simply attributable to caloric imbalance but is influenced by systemic factors associated with insulin metabolism." (PMID 38275634, 2023). "This is because the changes in insulin levels are caused only by the decrease in β-cell mass and are not driven by obesity." (PMID 37519334, 2023). "Another hypothesis states that obesity results in elevated levels of insulin and insulin-like growth factor 1 (IGF-1), a known mitogen." (PMID 37629396, 2023). "Based on our in vitro findings that metformin both accentuated and attenuated insulin secretion, we hypothesized that in children with obesity, metformin treatment would either decrease or increase insulin AUC0–120." (PMID 37623862, 2023). "The role of obesity may be explained by fetal overfeeding due to increased nutrient transport across the placenta, leading to higher insulin synthesis and fetal growth." (PMID 37685803, 2023). "This strategy mitigates various obesity-induced effects, including a reduction in body weight, improvement in insulin sensitivity, insulin resistance, glucose tolerance, systemic inflammation, restoration of circadian rhythm, and amelioration of memory deficits." (PMID 36674448, 2023). "Another possible hypothesis suggests that obesity contributes to the increased circulating insulin and insulin-like growth factor 1 (IGF-1), which, in turn, can promote cell proliferation and tumor growth." (PMID 38068818, 2023). "Furthermore, increased levels of free fatty acids (FFAs) in obesity contribute to lipotoxicity, one of the main factors for insulin resistance." (PMID 36904281, 2023). "As for the mechanism, IR may play a mediator role in the relationship between obesity and HUA, as insulin has been identified as a cause of hyperuricemia by inhibiting uric acid excretion." (PMID 37736731, 2023). "Furthermore, transcriptomics studies have examined the role of miRNAs in obesity to better understand their regulatory roles in adipogenesis, adipocyte differentiation, and insulin signalling." (PMID 36717394, 2023). "Indeed, the unfavorable effects of obesity on cancer development and progression are attributable to disruptions in adipokines, sex hormones, inflammation, and insulin metabolism." (PMID 37424008, 2023). "Obesity-related factors, such as immunity, insulin, adiponectin, adipocytokines, nonalcoholic fatty liver and inflammatory reaction, may affect the occurrence of obesity and increase the risk of cancer." (PMID 36836694, 2023). "Conversely, skeletal muscle-specific ablation of Usp21 improves obesity and insulin sensitivity." (PMID 36834633, 2023).
Obesity (continued). "Surrogate measures of IR possess suboptimal diagnostic sensitivity, especially among people without obesity, and are hampered by the lack of standardisation of the insulin assay." (PMID 37329449, 2023). "The restoration of the GSH system by chrysin plays an important role in anti-obesity treatment because GSH is an essential hepatic antioxidant that controls redox status and plays a key role in restoring insulin sensitivity in obesity-associated metabolic syndrome." (PMID 36838721, 2023). "Insulin, amylin, and pepsin are increased in obesity and may have direct effects on bone cells to increase bone formation and decrease resorption." (PMID 37884990, 2023). "Sleep disorders have been observed in obesity, decreased insulin sensitivity, and hypertension." (PMID 37198557, 2023). "Gavaged with L. reuteri attenuated depressive-like behavior, improved blood lipids and insulin resistance, reduced inflammation in liver and adipose tissues, improved intestinal tight junctions as well as the microbiome dysbiosis in obesity and depression comorbidity mice." (PMID 37050901, 2023). "Moreover, the increased insulin levels in obesity inhibit AMPK activity in muscle, thereby suppressing slow-fiber-type expression." (PMID 37298051, 2023). "Together, these data lend support to the insulin hypothesis that obesity-induced hyperinsulinemia drives the development of PDAC." (PMID 37648285, 2023). "Similarly, insulin stimulates EPRS1 binding to SPEAR in differentiated adipocytes, possibly illuminating the clinical observation that insulin treatment, like obesity, is associated with increased mortality in COVID-19 patients." (PMID 38108455, 2023). "However, in the course of obesity and/or IR in a state of hyperleptinemia, the dysregulation of the adipocyte–insulin axis in pancreatic beta cells promotes hyperinsulinemia." (PMID 37373485, 2023). "We found higher levels of serum TC, TG, insulin, and iron in individuals with obesity and MetS." (PMID 37670399, 2023). "Taken together, obesity is associated with non-homeostatic levels of key inflammatory mediators that serve as candidate physiologic targets to improve insulin action and glucose metabolism." (PMID 37299403, 2023). "Similarly, miR-103a-3p has been found to be down-regulated in blood samples of individuals with obesity and its role in modulating insulin sensitivity is well-established." (PMID 37686592, 2023). "Given the strong relationship between glucose metabolism, inflammation and OS, we hypothesized that children with obesity and a late insulin peak at the OGTT, may also have increased OS levels and inflammation." (PMID 37599368, 2023). "The causal links between obesity and insulin are complex and controversial, and research has not been able to establish these links fully." (PMID 36829976, 2023). "Furthermore, CD36 peptide treatment improved glucose tolerance and insulin sensitivity, and mitigated obesity-related fatty liver disease and kidney damage." (PMID 37980376, 2023). "Therefore, an excess of visceral AT in obesity initiates chronic low-grade inflammatory conditions that interfere with insulin signaling via insulin receptors (INSRs)." (PMID 37372966, 2023). "The effect of obesity on macronutrient metabolism is closely related to the ongoing insulin resistance in obese individuals, which is characterized by resistance to the effect of insulin on glucose uptake, utilization, and storage." (PMID 37252233, 2023). "Many interventional studies on obesity or related complications used lifestyle modification as a potential tool to shed extra weight, produce a better insulin response, revert pre-hyperglycaemic to normoglycemic, and proved to improve lipid or other cardio-metabolic profiles." (PMID 37305820, 2023).
Obesity (continued). "Similarly, reversing obesity through modulation of dietary intake has been shown to improve insulin sensitivity in cats, and adipose tissue in obese cats has been shown to have higher pro-inflammatory cytokine expression of TNFa than lean cats." (PMID 37693421, 2023). "There seems to be an agreement around the notion that small and frequent meals are preferred over fewer but larger ones due to improvements seen in both blood glucose, lipid profile, and obesity, which was proposed to possibly be due to reduced glucose and insulin spikes." (PMID 37046893, 2023). "Moreover, H19 participates in lipogenesis regulation, adipose tissue metabolism, and insulin sensitivity, and consequently plays a role in obesity pathogenesis." (PMID 37104004, 2023). "Glucagon-like petide-1 (GLP-1) is a peptide that is mainly produced by the intestinal cells and is known to improve cardiovascular health, improve endothelial function in obesity, and stimulate fatty acid oxidation and insulin signalling pathways, thus enhancing the antioxidant capacity." (PMID 37627590, 2023). "These prior research findings may also help explain why people on multiple daily insulin injections, or those with overweight or obesity, experience greater improvements in post-exercise glycemia with elevated daily protein intakes." (PMID 37111199, 2023). "Therefore, vitamin D plays an important role in glucose homeostasis, insulin production and obesity-related inflammation." (PMID 37374327, 2023). "In a mouse model study, when IRS2 was knocked out, obesity and insulin sensitivity decreased." (PMID 37608331, 2023). "Concerning Ruminiclostridium 9, it has demonstrated its regulatory effects on lipid metabolism, inflammation reduction, enhancement of intestinal barrier function, weight gain reduction, and improved insulin sensitivity in mice, effectively countering obesity development." (PMID 37950180, 2023). "Furthermore, changes in hormonal profiles have been observed in the obesity state, including decreased growth hormone (GH) levels, and increased insulin and leptin levels." (PMID 37189668, 2023). "Together, these results provide evidence that SG affects hepatic insulin clearance and may be helpful to counteract obesity-induced hyperinsulinemia." (PMID 36675244, 2023). "This study was conducted in preparation for an ongoing 12-week randomized controlled trial in older adults with obesity investigating the effect of whole soybean products as part of a low energy dense diet on insulin sensitivity (ClinicalTrials.gov identifier: NCT05649176)." (PMID 37111139, 2023). "Thus, the lack of odor-evoked CPIR in our obese mice is consistent with the impaired cephalic phase insulin release observed in human obesity." (PMID 37182561, 2023). "Interestingly, rats with diet-induced obesity in the pair-fed group maintained high levels of Pdx1 and Neurog3, pointing to an increased formation of insulin-secreting β-cells." (PMID 37274331, 2023). "Indeed, Phospho1 deficiency in mice results in a reduced blood glucose concentration, enhanced insulin sensitivity and improved glucose tolerance protecting high-fat diet-induced obesity." (PMID 39184263, 2023). "Although confounders such as obesity, age, sex, cigarette smoking, alcohol drinking, and drug administration were controlled, whether the results can be extended to more insulin-resistant subjects, such as an obese population, remains unknown." (PMID 36761190, 2023). "This dual mechanism of action still acts to promote insulin secretion, but has different pharmacodynamic properties, which have been shown to be beneficial in terms of improving insulin sensitivity, as well as reducing obesity." (PMID 37375749, 2023). "Obesity or hyperlipidemia leads to excess intracellular Ca2+ levels through SOC-mediated Ca2+ influx, causing the formation of Ca2+-PIPs that inhibit the membrane interactions of PH domains, resulting in impaired insulin signaling." (PMID 37121975, 2023).
Obesity (continued). "Peripheral insulin sensitivity is effectively increased by protection against HFD-induced obesity." (PMID 37221569, 2023). "The potentially influential role of insulin in modulating mood and cognition may be a contributing factor in the higher rates of depression and cognitive decline seen in individuals with obesity and diabetes." (PMID 36979453, 2023). "However, the hormonal milieu in obesity also contributes to LV hypertrophy, with insulin and leptin both stimulating myocyte hypertrophy." (PMID 36761185, 2023). "Previous studies reported that Scd1 global knockout (KO) mice showed improved insulin sensitivity, higher-energy metabolism, and more resistant to diet-induced obesity by the activation of lipid oxidation in addition to the reduction of triglyceride synthesis and storage." (PMID 37580962, 2023). "Studies have been conducted to assess the relationship between insulin and obesity development." (PMID 36829976, 2023). "Conversely, adiponectin, known for its anti-inflammatory and insulin-sensitizing properties, is typically reduced in obesity and may contribute to the reproductive dysfunctions seen in PCOS." (PMID 38264286, 2023). "Taken together, these results suggest that candesartan-mediated normalization of intracellular Ca2+ homeostasis may translate into enhanced insulin signaling and improved systemic metabolism and overall metabolic health in the setting of obesity." (PMID 37121975, 2023). "Increased diet-induced IGF-1 and insulin levels, which are observed in obesity in Western countries, may lead to the increased proliferation and inhibition of apoptosis of CSCs via PI3K/AKT/Wnt signaling." (PMID 36835075, 2023). "However, the robust finding of associations between metabolic traits and tryptophan by-products suggests relevance of tryptophan metabolism in the regulation of the glucose-insulin axis and obesity." (PMID 37029207, 2023). "Moreover, the induction of muscle-derived FGF21 as an adaptive adjustment measure distally regulates insulin signaling, muscle fiber development, energy metabolism homeostasis, obesity, and other systemic problems to improve metabolic characterization." (PMID 38069273, 2023). "According to a recent study, persistent prepubertal obesity along with severe hyperglycemia and resistance to insulin may be a precursor to the later onset of PCOS." (PMID 37854752, 2023). "Our analysis demonstrated that the variables that led to worse VAS and EQ-5D-5L sub scale scores (indicating lower perceived HRQoL) were being female, obesity (BMI ≥30), insulin usage, lower levels of education, and the presence of complications and/or comorbidities." (PMID 37033039, 2023). "One possible explanation is that excess adipose tissue in obesity may lead to increased levels of circulating insulin and free fatty acids (FFAs), which can inhibit GH secretion by suppressing the principal regulator, the GHRH hormone." (PMID 37298507, 2023). "Given that there is a linking mechanism between obesity, inflammation, and IR, the predominance of type 1 inflammatory response in AT may be involved in the etiopathogenesis of altered insulin signaling." (PMID 37372966, 2023). "In individuals with obesity, high levels of circulating inflammatory markers and local inflammation of the microvasculature in skeletal muscle result in the inactivation of the insulin signaling pathway that can decrease the translocation of GLUT4 to the plasma membrane for glucose uptake." (PMID 36441492, 2023). "This indicates that the elevated free fatty acids and pro-inflammatory cytokines present in obese individuals could be involved with the obesity-induced reduction in insulin clearance." (PMID 36675244, 2023). "Secondly, we proposed that such overstimulated beta-cells with accentuated insulin secretion may precipitate declining beta-cell function and the attenuated first-phase insulin secretion observed in adolescents with obesity." (PMID 37623862, 2023).
Obesity (continued). "Beyond their elevated levels found in obesity and T2D, it is becoming increasingly clear that BCAAs may exert detrimental effects on glycemic control and insulin action." (PMID 37049555, 2023). "The supplementation improved insulin sensitivity and other obesity parameters." (PMID 36829976, 2023). "He mainly focused on MS, such as insulin sensitivity, and obesity." (PMID 36654766, 2023). "However, adipocytes‐specific deletion of β‐catenin in mice results in improved insulin sensitivity and reduced obesity." (PMID 36807886, 2023). "Similarly, when sugar (fructose + glucose) was replaced with starch (glucose) in children with obesity and metabolic syndrome, their glucose tolerance significantly improved in just nine days, along with their blood pressure, triglycerides, and insulin levels." (PMID 37521964, 2023). "However, in the context of obesity where lipolysis is unrestrained because of insulin resistance, levels of FABP4 are chronically elevated in the circulation." (PMID 37172691, 2023). "The activation of the aryl hydrocarbon receptor (AhR), a xenobiotic sensor, by obesogens may contribute to diet-induced obesity through influences on lipid metabolism and insulin resistance acting at various sites, including adipose tissue." (PMID 37443781, 2023). "The current perspectives on the treatment of obesity-linked DM involve non-pharmacological approaches including exercise, diet control, surgery, and pharmacological approaches like insulin and non-insulin methods." (PMID 36716329, 2023). "In addition, the World Health Organization recommendations on regular PA are reinforced here to improve insulin sensitivity not only in adolescents with obesity or metabolic disorders but also to prevent adverse metabolic outcomes in normal-weight adolescents." (PMID 37396186, 2023). "However, leptin prevents obesity by promoting satiety, reducing hunger, and increasing insulin sensitivity." (PMID 37363537, 2023). "For example, Amylin, a hormone synthesized and co-secreted with insulin by pancreatic β-cells, is elevated in obesity and may share similar pathophysiology with Amyloid-β, characteristic of AD neuropathology." (PMID 37457589, 2023). "Although rexinoids may prove useful as insulin sensitizers and to reduce obesity, they also present with deleterious side effects." (PMID 37714463, 2023). "Importantly, melatonin and metformin demonstrated synergistic activities to ameliorate obesity, insulin sensitivity, circadian activity, and suppression of islet cell failure in CDO rats, and so slowing the onset of metabolic dysfunction." (PMID 37441501, 2023). "In addition, the LPCAT family is involved in physiological and pathological processes, such as insulin signaling pathways, brain neuron formation and maintenance, hepatic lipid metabolism, and obesity." (PMID 37687178, 2023). "Existing studies showed that SGA and overweight children were more insulin resistant and at increased risk of metabolic syndrome than AGA children, which might be due to adverse fetal programming and obesity." (PMID 36839337, 2023). "Since obesity-induced IR is associated with compensatory hyperinsulinemia, we speculate that, like muscle, the ASM retains insulin sensitivity and may, therefore, have an augmented response to insulin exposure." (PMID 36837831, 2023). "Furthermore, estrogen has a protective effect against an HFD in females by reducing proinflammatory cytokines and maintaining insulin sensitivity during obesity." (PMID 36902691, 2023). "In an animal study, it has been reported that administration of either pasteurized A. muciniphila or its outer membrane protein, Amuc_1100*, activated Toll‐like receptor 2, increased the expression of tight junction protein, restored high‐fat diet‐induced obesity and reduced insulin resistance." (PMID 37132118, 2023). "The level of circulating insulin decreases in diabetes while it increases in obesity and cancers." (PMID 36849958, 2023).